KRTAP13-3 (keratin associated protein 13-3)
Description:
In the hair cortex, hair keratin intermediate filaments are embedded in an interfilamentous matrix, consisting of hair keratin-associated proteins (KRTAP), which are essential for the formation of a rigid and resistant hair shaft through their extensive disulfide bond cross-linking with abundant cysteine residues of hair keratins. The matrix proteins include the high-sulfur and high-glycine-tyrosine keratins (By similarity).
Synonyms: KAP13.3
Tractability: No criterion of Open Targets' tractability assessment is met for any kind of drug.
Gene: Protein-coding gene on chromosome 21 (30,425,380 to 30,425,926, reverse strand). Ensembl gene ENSG00000240432.
Pathways (Reactome):
Developmental Biology: Keratinization
Gene Ontology:
Molecular function: protein binding
Cellular component: cytosol
Genetic constraint (gnomAD): Loss-of-function variants: 1 observed, 0.48 expected, observed/expected ratio (o/e) 2.1. That is too few expected variants to judge how well the gene tolerates losing a copy. Missense variants: 243 observed, 210.48 expected, observed/expected ratio (o/e) 1.15, 90% interval 1.04 to 1.28. Synonymous variants: 98 observed, 82.57 expected, observed/expected ratio (o/e) 1.19, 90% interval 1.01 to 1.4.
Homologues: Orthologues: dog KRTAP13-3 (65% identical), rat LOC100363236 (56% identical), mouse Krtap13 (55% identical), rat Krtap14l (55% identical), mouse Krtap13-20 (54% identical), mouse Krtap13-21 (54% identical), rat Krtap13 (54% identical), rat Krtap13-2 (53% identical), mouse Krtap13-23 (52% identical), mouse Krtap13-24 (37% identical). Paralogues in human: KRTAP13-1 (69% identical), KRTAP13-2 (65% identical), KRTAP13-4 (59% identical), KRTAP15-1 (40% identical), KRTAP11-1 (30% identical), KRTAP26-1 (24% identical), KRTAP27-1 (23% identical), KRTAP25-1 (19% identical).